USP22 (ubiquitin specific peptidase 22)
Diseases named in the same sentence as USP22 in open-access papers (continued):
Sharing a sentence is not in itself a finding about the gene and the disease.
tumor (continued). "Thus, USP22 may be ascribed a major role in chemotherapy resistance in tumor cells." (PMID 28567015, 2017). "Here, we report that USP22 expression is highly elevated in ATC tissues, which positively correlated with tumor size, extracapsular invasion, clinical stages, and poor prognosis of ATC patients." (PMID 27145278, 2016). "In conclusion, the results presented here show that USP22 is upregulated in ATC and is positively correlated with tumor growth and metastasis." (PMID 27145278, 2016). "USP22 silencing by shRNA inhibits proliferation, induces apoptosis and arrests cells at the G0/G1 phases in NSCLC cells and curbs human NSCLC tumor growth in a mouse xenograft model." (PMID 25547493, 2014). "The expression of USP22 and Ki-67 in SACC samples and normal salivary gland adjacent to tumor were analyzed by immunohistochemistry." (PMID 24466336, 2014). "Our in vitro and in vivo studies showed that USP22 silencing by shRNA inhibits proliferation and induces cell cycle arrest and apoptosis in human NSCLC cells in vitro and curbs human NSCLC tumor growth in a mouse xenograft model in vivo." (PMID 25547493, 2014). "Using a luciferase reporter system, we found that the promoter constructs of USP22 displayed relatively higher activity in HeLa cells than in HFL1, cells indicating abnormal transcriptional activity of the USP22 gene in human tumor cells." (PMID 23300749, 2012). "In seven cases (UCHL1, USP9X, USP11, USP10, USP22, COPS5 and COPS6), dysregulation was observed in more than one tumor type." (PMID 21283576, 2011). "Consistent with our in vitro studies, stable reconstitution of Ezh2, but not Ezh2 F667I or ΔSET mutant, largely abrogated the tumor-suppressive effects by the targeted Usp22 inhibition." (PMID 41252204, 2025). "Cell surface staining of MHC-I expression on tumor cells indicated that overexpression of Ezh2, but not Ezh2 F667I or ΔSET mutant, in Usp22-null cells impaired MHC-I expression." (PMID 41252204, 2025). "Tumor tissues from ICB nonresponders exhibited higher levels of both tumoral USP22 and EZH2 expression and lower tumoral β2M expression when compared with biopsies from patients who were ICB responsive." (PMID 41252204, 2025). "In addition to USP22, the ubiquitin-like modifier activating enzyme 1 (UBA1) has been shown to downregulate MHC-I expression for tumor immune evasion." (PMID 41252204, 2025). "In addition, the IHC staing showed that USP22 and Ki67 levels decreased, whereas the levels of cleaved caspase‐3, cleaved caspase‐9, and cleaved PARP increased in 13‐MB‐treated tumor xenograft mice, indicating that 13‐MB triggered significant apoptosis." (PMID 39101247, 2024). "Recent data from our group and others indicate that tumor cell–intrinsic factors in PDAC, such as CXCL1, EPHA2, USP22, EGFR, and the prostaglandin synthesis enzyme COX-2, promote myeloid cell infiltration that negatively impacts T cell infiltration, function, and tumor rejection." (PMID 39298269, 2024). "The kinetics and frequency of tumor formation were not altered by Usp22 overexpression, in either the Usp22OE/+; NIC or Usp22OE/OE; NIC mice." (PMID 38236941, 2024). "No significant changes were observed in tumor weight, tumor volume, or numbers of tumors per mouse upon Usp22 overexpression." (PMID 38236941, 2024). "The expression level of USP22 protein in the tumor tissues of patients with LUAD was significantly higher than that in adjacent normal tissues, and patients with high USP22 expression had a worse prognosis than those with low USP22 expression." (PMID 39101247, 2024).
tumor (continued). "After knockdown of USP22, ALDH1A3 was significantly downregulated in tumor cells." (PMID 35935969, 2022). "Moreover, both USP22 and FASN were significantly upregulated in CRC tumor tissues compared with the paired paracancerous non-tumor tissues." (PMID 36333288, 2022). "Co-expression of USP22 and BMI1 can accelerate tumor proliferation, stemness, and drug resistance." (PMID 35935969, 2022). "Several studies suggesting a tumor-promoting function of USP22 did not include appropriate controls and utilized antibodies which were likely to be cross-reactive." (PMID 33920268, 2021). "By association with USP22 in the SAGA complex, SIRT1 targets protein deacetylation on the structures of their histones or non-histones to facilitate tumour progression." (PMID 34226501, 2021). "Taken together, these results demonstrate that USP22 is involved in the regulation of necroptosis in human tumor cells, but likely not in murine cells, through DUB‐mediated effects." (PMID 33369872, 2021). "Collectively, our present work identifies a new pro-tumorigenic function of USP22 in the suppression of the UPR-signaling, revealing its global role in supporting the cellular protein chaperoning system and protecting tumor cells against proteostasis imbalance." (PMID 34007022, 2021). "USP22 enhanced both MMP2/9 expression, the tumour invasive markers." (PMID 34226501, 2021). "Knockdown of USP22 in an in vivo model was shown to decrease tumor angiogenesis, impair non-homologous DNA damage repair pathways and significantly improve the therapeutic efficacy of cisplatin." (PMID 34660907, 2020). "Ubiquitin-specific peptidase 22 (USP22) is a newly discovered member of the deubiquitinase (DUB) family, and it is involved in many biological processes, including tumor development, cell growth and differentiation, cell cycle regulation, transcriptional activation and signal transduction." (PMID 28567015, 2017). "Moreover, we also identified a high expression correlation between USP22 and MRP1 in tumor samples from 168 HCC patients, which further confirmed the role of USP22 in the induction of MDR in HCC and supported the molecular mechanism we previously investigated." (PMID 28417539, 2017). "Moreover, USP22 is required for the proper functioning of MYC, which is widely believed to play a significant role in regulating the tumor cell cycle and tumor invasion." (PMID 25909224, 2015). "High USP22 expression in HCC was significantly correlated with clinical stage and tumor grade." (PMID 25909224, 2015). "Conversely, further analysis of surviving tumor cells 48 hours after cocultivation with OT-I CD8+ T cells showed a higher USP22 and EZH2, but not EZH1 and USP27 expression, implying that the increased USP22 and EZH2 expression is involved in tumor immune evasion." (PMID 41252204, 2025). "Our data thus far demonstrate that USP22 protects EZH2, a known negative regulator of MHC-I expression, from ubiquitination-mediated proteasomal degradation, suggesting that USP22 promotes tumor evasion of CD8+ T cell antitumor immunity through potentiating EZH2-mediated MHC-I downregulation." (PMID 41252204, 2025). "Moreover, DUBs like USP22 play a role in promoting tumor development through the regulation of epigenetic changes, while others such as USP28 and USP7 are involved in controlling the turnover of oncogenes or tumor suppressors." (PMID 37626927, 2023).
tumor (continued). "It has been found that tumor suppressor miR-410-3p and miR-29c could attenuate the resistance to GEM in PC through inhibiting expression of High mobility group box 1 (HMGB1) and ubiquitin specific peptidase-22 (USP22) and, thus, reducing autophagy, respectively." (PMID 37560164, 2023). "Notably, mice implanted with the USP22-overexpressing MHCC-97L cells formed larger tumors compared to those implanted with the control MHCC-97L cells; however, MHCC-97L cells with simultaneous USP22 overexpression and PPARγ, ACC or ACLY knockdown showed lower tumor growth rates." (PMID 35449157, 2022). "Additionally, immunohistochemical analyses confirmed that the expression of HER2, the driving oncogene in this tumor model, was not affected by Usp22 deletion." (PMID 34007022, 2021). "In addition, USP22 was reported to deubiquitinate and thereby stabilize several non-histone substrates including tumor-promoting factors such as MYC." (PMID 33920268, 2021). "The human ortholog of Non-stop, USP22 has mixed oncogenic and tumor-suppressive functions." (PMID 33629655, 2021). "Furthermore, combined inhibition of USP22 and HSP90 may provide an effective combinatorial approach to tumor therapy, which would overcome the context-dependency demonstrated in our studies." (PMID 31801945, 2019). "Similarly, USP22, hortholog of the Ub-protease Ubp8, subunit of the DUB module of SAGA complex, is overexpressed in liver, breast, gastric, bladder and lung cancers and is a predictor of tumor recurrence in hepatocarcinoma." (PMID 30524288, 2018). "Moreover, USP22 and AP4 overexpression may stimulate tumor metastasis and adversely affect OS in CRC patients." (PMID 28427243, 2017). "USP22 expression, which was classified as high or low based on the ROC-derived cutoff, was mainly found to be higher in patients with more advanced tumor stages (stages III and IV) and higher tumor grades (grades 3-4), indicating that USP22 might be involved in HCC progression." (PMID 25909224, 2015). "Consistent with our in vitro findings, tumors derived from USP22 shRNA-transfacted A549 cells grew at a much slower rate than those derived from SCR shRNA-transfected cells, as reflected in the significantly smaller tumor size and tumor weight four weeks after cell implantation." (PMID 25547493, 2014). "However, in Usp22 knockout tumor cells, IFN-γ treatment failed to further enhance MHC-I expression." (PMID 41252204, 2025). "However, on the other hand, inhibiting USP22 in turn would increase proportions of NK cells and CD8 + T cells, and destroy the fitness of Tregs, making ‘cold’ tumors into ‘hot’ tumors, thereby converting tumor cells that are fully resistant to ICIs immunotherapy to a sensitive state." (PMID 37658402, 2023). "Additionally, ESR1, OTUD6B, USP2, and USP37 showed a positive correlation with risk scores, while USP22 exhibited a significant negative correlation with risk scores (r = -0.7, p < 0.0001), suggesting a potential role for these genes in ESCC tumor progression and patient prognosis." (PMID 39742278, 2024). "We collected paired tumour and adjacent non-tumour tissues from 57 intrahepatic CCA (iCCA) patients and evaluated levels of the USP22 gene and protein by qPCR and immunohistochemistry." (PMID 34226501, 2021). "Compared with USP22-negative samples in LUAD, there were poorer differentiation, larger tumor size, and more advanced disease stage in USP22-positive samples." (PMID 32294625, 2020). "Interestingly, USP22 appears to selectively control EZH2 but not any other PCR2 complex proteins including EZH1, SUZ12, and EED in tumor cells." (PMID 41252204, 2025). "Caspase‐3, caspase‐9, and PARP levels in tumor tissues did not change significantly after 13‐MB treatment; however, cleaved caspase‐3, cleaved caspase‐9, and cleaved PARP expression were significantly enhanced, and USP22 expression was significantly inhibited." (PMID 39101247, 2024).
infection (4 papers, 2010 to 2023). The state of being infected such as from the introduction of a foreign agent such as serum, vaccine, antigenic substance or organism. "At the early stage, day 1 after infection, serum concentrations of interferon alpha and beta were lower in Usp22-deficient mice than in WT mice." (PMID 37896966, 2023). "We also noted strongly diminished numbers of F4/80+ macrophages in particular on day 9 after infection in Usp22 deficient mice." (PMID 37896966, 2023). "The effect of Usp22 deficiency on PD-L1 expression in monocytes was more prominent in the spleen during the later course of LCMV infection than in blood tested at an early time point after acute infection." (PMID 37896966, 2023). "Loss of Usp22 exerted a protective effect in case of in vivo infection with Listeria monocytogenes." (PMID 37896966, 2023). "The infection of Vero cells overexpressing Usp22 with vesicular stomatitis virus (VSV) also led to reduced production of proinflammatory cytokines inclusive interferons, making the Vero cells more susceptible to VSV." (PMID 37896966, 2023). "Animals with a knockout or knockdown of Usp22 experienced a lethal course of infection with VSV or HSV-1 compared with respective controls." (PMID 37896966, 2023). "Increased Usp22 expression in vitro after corresponding transfection of 293T cells resulted in inhibited type I interferon formation upon infection with murine Sendai virus." (PMID 37896966, 2023). "For this, we generated control and USP22 KO Caco-2 cells that express the virus receptors ACE-2 and TMPRSS2 and are susceptible to infection with SARS-CoV-2 virus." (PMID 35933402, 2022). "At 8 h post infection, only ∼20% of the USP22- and CDC27-silenced infected cells showed normal levels of replication." (PMID 20552012, 2010). "The data showed that at 8 and 24 h post-infection, specific silencing of USP22 and CDC27 inhibited bacterial replication throughout the intracellular infection period, compared to the negative control RNAi-treated or untreated cells." (PMID 20552012, 2010). "Despite infection- or inflammation-free conditions, Usp22 KO mice displayed increased expression of inflammation genes, in particular interferon-stimulated genes, while systemic levels of interferon alpha and gamma remained similar between Usp22 KO mice and wild-types." (PMID 37896966, 2023). "The so-far-known, broadly preactivated interferon response due to the lack of Usp22 already in the absence of infection underlines the importance of Usp22 deficiency in the activation of the innate immune system." (PMID 37896966, 2023). "Furthermore, we evaluated PD-L1 expression on CD11b+Ly6C+ Ly6G− cells harvested from the spleen in Usp22 KO or wild-type mice on day 9 after infection." (PMID 37896966, 2023). "Then, Usp22 seems to have negative regulatory effects in immunological processes, which might be beneficial for the coordination of overwhelming inflammation upon infections and controlling of autoimmune processes." (PMID 37896966, 2023). "Although the early interferon response in the first days after acute LCMV infection was reduced in Usp22 deficient mice, the virus titers were comparable in Usp22 deficient and wild-type mice after infection, a finding indicating that LCMV clearance is not significantly influenced by Usp22 knockout." (PMID 37896966, 2023). "In the samples obtained from the liver and spleen on day 9 after infection, the frequencies of CD8+ T cells were similar between Usp22 KO mice and control mice." (PMID 37896966, 2023). "Usp22 has been reported to affect the expression of type I interferon genes and interferon-stimulated genes in the absence of infection or inflammation." (PMID 37896966, 2023). "Usp22 KO mice exhibited a strong elevation of serum liver enzyme activity and lactate dehydrogenase activity during the follow-up period of acute LCMV infection, starting from day 7 after infection." (PMID 37896966, 2023).
infection (continued). "In the study reported here, we found that the absence of Usp22 in the hematopoietic system led to severe immunopathology in the liver following intravenous infection with LCMV." (PMID 37896966, 2023). "Despite of absence of infection or inflammatory signals, mice lacking Usp22 in their hematopoietic system displayed overproduction of eeloid cells, in particular granulocytes, alteration in the development of B-cells, and enhancement in the expression of proinflammatory genes." (PMID 37896966, 2023). "The results showed that at 12–24 h of infection the % of co-localization of the WT FCPs with both LAMP-2 and cathepsin-D positive compartments did not change from the 2 h time point in the CDC27, USP22, or PI4KCA RNAi-treated cells." (PMID 20552012, 2010).
bacterial infection (1 paper, 2023). "Increased phagocytosis capacity of neutrophil granulocytes was particularly apparent after bacterial infection of Usp22 deficient mice with Listeria monocytogenes, which might be considered to be an essential trigger." (PMID 37896966, 2023).
endocrine gland tumor (1 paper, 2021). "Gene ontology (GO) terms for physiological functions and diseases enriched for genes that were downregulated in Usp22 OE MECs were related to inflammatory response, recruitment of white blood cells (myeloid cells and lymphocytes), endocrine gland tumor, and carcinogenesis at large." (PMID 34503086, 2021).
USP22 also shares sentences with these, for which no sentence is quoted: triple-negative breast carcinoma (3 papers); breast tumor (2); Cerebral ischemia (2); inflammation (2); invasive breast carcinoma (2); thyroid carcinoma (2); asthma (1); autoimmune thrombocytopenia (1); COVID-19 (1); endometrial cancer (1); gynecological tumors (1); head and neck squamous cell carcinoma (1); hepatitis C infection (1); kidney tumors (1); metastatic tumors (1); myocardial infarction (1); neurological disorders (1); papillary renal cell carcinoma (1); psychiatric disorder (1); rectal cancer (1); renal clear cell carcinoma (1); renal fibrosis (1); systemic lupus erythematosus (1); type 2 diabetes (1); ulcerative colitis (1).